SPARC (secreted protein acidic and cysteine rich)
Diseases named in the same sentence as SPARC in open-access papers (continued):
Sharing a sentence is not in itself a finding about the gene and the disease.
breast carcinoma (continued). "A high combined expression score of 5 stromal proteins, namely THBS1, TNC, FN, SPARC and α-SMA, in baseline untreated breast cancers, is associated with shorter survival, while their up-regulation after chemotherapy predicted for poor treatment response." (PMID 27487140, 2016). "Biologically, SPARC was found to promote cancer development in some tumors with highly metastatic characteristics, such as breast cancer and melanoma, but act as a tumor suppressor in some other cancer types." (PMID 28053291, 2016). "Among known stabilin-1 ligands an extracellular regulator of tissue turnover SPARC is expressed in breast cancer and involved in the control of breast cancer growth." (PMID 27105498, 2016). "Until now there are only few studies regarding breast carcinoma that tried to disclose the roles of SPARC in bone metastasis." (PMID 26703564, 2015). "The ectopic secretion of proteins, known to be microenvironmental stimuli like SPARC and Endothelin 1, appeared to confer osteogenic traits to disseminated breast carcinoma cells, important for the attachment to bone matrix." (PMID 26703564, 2015). "In human specimens, breast carcinoma cells and stroma presented SPARC signals, in agreement with the literature." (PMID 26703564, 2015). "A high degree of immunoreactivity for SPARC, as shown in the Table, was present in 70% of breast carcinoma patients examined (3/5), and pair-matched for developing bone metastasis; the plasma level was not elevated." (PMID 26703564, 2015). "All the three Patients showed extraordinary similarities in SPARC expression: a strong immunostaining occurred in epithelial-dysplastic cells and in breast carcinoma cells." (PMID 26703564, 2015). "Studies are in progress to evaluate this mechanism, since the study with MDA-MB231 cells indicates that in vitro breast carcinoma scarcely produces the matricellular protein SPARC." (PMID 26703564, 2015). "A recycling of SPARC would occur in the primary breast carcinoma, and a role of exosomes cannot be excluded since these microvescicles can modulate nearby or distant target cells by direct contact of their surface molecules, to activate intracellular pathways." (PMID 26703564, 2015). "The results indicate that the biological function of SPARC depended on the phase of breast cancer progression, the tissue compartment in which it was expressed, and its body distribution, with plasma release of SPARC being opposite to metastasis engraftment." (PMID 26703564, 2015). "We have demonstrated a favouring function of endogenous SPARC for bone metastasis from breast cancer using a xenograft model, prepared with clone 1833 derived from MDA-MB231 human breast carcinoma cells." (PMID 26703564, 2015). "Multivariate model evaluating the association between SPARC, SPARC7 and relapse free survival in all patients and according to breast cancer subtype." (PMID 23638089, 2013). "We found that high SPARC mRNA expression was associated with poor prognosis in patients diagnosed with basal and HER2-positive breast cancer." (PMID 23638089, 2013). "In conclusion, the current analysis suggests a potential role of SPARC in determining prognosis and response to primary chemotherapy in early breast cancer." (PMID 23638089, 2013). "High SPARC expression was associated with poor prognosis in patients with basal and HER2+ breast cancer even after adjusting for clinicopathologic parameters." (PMID 23638089, 2013). "Acknowledging these facts and based on our results, it would be interesting to validate the association between SPARC expression and the benefit of albumin-bound cytotoxics in HER2-positive breast cancer." (PMID 23638089, 2013). "For example, higher levels of SPARC expression have been reported in breast cancer, hepatocellular carcinoma, prostate cancer, colorectal cancer, and ovarian cancer." (PMID 22879971, 2012).
breast carcinoma (continued). "In this study, we identified Brg-1 as a critical regulator for the constitutive expression of the SPARC gene in mammary carcinoma cell lines." (PMID 20687958, 2010). "Recent studies have shown that over-expression of SPARC in the surrounding stromal of breast cancer was related with the better prognosis of patients." (PMID 20565704, 2010). "A report using human MDA-MB231 breast cancer cells demonstrated that overexpression of SPARC inhibited the metastatic capacity of these cells to different organs, including lungs and bones." (PMID 20687958, 2010). "Another recent study also revealed that down-regulation of SPARC is correlated with poor prognosis in breast cancer patients." (PMID 20687958, 2010). "We identified Brg-1 as a critical regulator for the constitutive expression levels of SPARC mRNA and protein in mammary carcinoma cell lines and for SPARC secretion into culture media." (PMID 20687958, 2010). "For example, higher levels of SPARC expression have been reported in breast cancer, melanoma and glioblastomas." (PMID 20565704, 2010). "For example, SPARC was found high levels in breast cancer, colon cancer, metastatic melanoma and invasive meningioma." (PMID 20087345, 2010). "In summary, we found that Sp1/Brg-1 complex is involved in the constitutive expression of the SPARC gene in mammary tumor cells." (PMID 20687958, 2010). "Two recent in vitro studies delineate the potential of SPARC as a suppressor of tumorigenic potential in human melanoma and breast cancer cells via the addition of either antisense RNA or the transfection of SPARC." (PMID 15558074, 2004). "The protein immunoreactivity of SPARC was detected mainly in the stroma cells, but rarely in the tumour cells in malignant ovaries, colorectal cancer, breast cancer and hepatocellular carcinoma." (PMID 15558074, 2004). "The overexpression of SPARC has been detected in melanoma, colorectal cancer, breast cancer, hepatocellular carcinoma, invasive meningiomas, and prostate cancer." (PMID 14562024, 2003). "Therefore, it is critical to investigate the acute effects of different exercise modes on the expression of anti-cancer myokines, such as IL-6, OSM, decorin, and SPARC, and their effects on breast cancer cell growth (i.e., MDA-MB-231)." (PMID 40608178, 2025). "Moreover, in both melanoma and high-grade breast cancer cells, we demonstrated that reducing SPARC secretion, either through oleic acid administration or forced production of SCD5, has beneficial effects on antitumor immunity." (PMID 40890836, 2025). "This is the first study to investigate not only the distinct and independent effects of different exercise modes on anti-cancer myokines such as decorin, IL-6, OSM, and SPARC in survivors of breast cancer, but also in exploring the effects of such exercise modes on MDA-MB-231 cell growth in vitro." (PMID 40608178, 2025). "The S1 and S2 peptides are H2-Kd-restricted epitopes from tumor-associated antigen SPARC, stimulating anti-tumor immunity without causing autoimmune disease in mouse mammary tumor models." (PMID 41050655, 2025). "Network pharmacology found that SPARC can be used as the basis for early breast cancer diagnosis." (PMID 37577749, 2023). "Pre-therapeutic analysis of SPARC in blood samples could facilitate the selection of patients for neoadjuvant therapy, especially for those with luminal breast cancer subtypes, and consequently improve long-term survival." (PMID 38137452, 2023). "SPARC is able to induce the activation of MMP-2 in breast cancer cell lines." (PMID 37577749, 2023). "A meta-analysis demonstrated that SPARC expression has prognostic significance in breast cancer." (PMID 37509139, 2023). "Overexpression of SPARC may promote cancer cell migration and invasion, and thus function as an oncogene and a potential therapeutic target for breast cancer." (PMID 37509139, 2023). "Breast cancer tissues and most breast cancer cells have a higher level of SPARC." (PMID 37577749, 2023).
breast carcinoma (continued). "Conversely, SPARC transfection in high‐grade isogenic breast cancer cells reduces tumor rate, and favors epithelial‐to‐mesenchymal transition and the formation of a highly immunosuppressive microenvironment composed of immune cells, such as myeloid‐derived suppressor cells." (PMID 36346290, 2023). "Knockdown of Snail decreases SPARC expression in human breast carcinoma MDA-MB-231 cells." (PMID 37158892, 2023). "In the present study, we identified a correlation between SPARC expression in the epithelium and in the stroma, providing evidence that SPARC may be important in tumor–host interactions between breast cancer cells and stromal fibroblasts." (PMID 38137452, 2023). "Breast cancer progression to the S phase was slowed down by SPARC." (PMID 37577749, 2023). "SPARC can be a viable curative target for treating breast cancer metastasized to the bone." (PMID 37577749, 2023). "The expression of SPARC was upregulated in breast cancer tissue compared with normal tissues." (PMID 35211625, 2022). "Interestingly, the transcription factor c-Jun was recently found to be a key transcriptional target of the PI3K/PKB/AKT/mTORC1 signaling axis in muscle satellite cells and c-Jun overexpression in MCF7 breast cancer cells increased SPARC levels." (PMID 36178526, 2022). "Our study underscored the relationship between SPARC expression and invasive regions, which may be clinically important for treating breast cancer." (PMID 35260632, 2022). "RT-PCR results showed that SPARC was highly expressed at the mRNA level in breast cancer tissues." (PMID 35211625, 2022). "Finally, only 4 articles were found to include the prognostic features of SPARC expression and its relationship with breast cancer." (PMID 35211625, 2022). "SPARC expression at protein and mRNA levels showed opposite trends in breast cancer." (PMID 35211625, 2022). "Research has shown that greater amounts of SPARC in breast cancer in mice inhibit cancer growth." (PMID 35917053, 2022). "At the same time, SPARC expression is upregulated in breast cancer patients." (PMID 35211625, 2022). "Overall, these results strongly suggest that SPARC cleavage in its extracellular Ca2+ binding domain may occur in vivo in cath-D-expressing mammary cancers, although other proteinases may also be involved." (PMID 33995652, 2021). "SPARC is highly expressed in many tumors, such as glioma, melanoma, and breast cancer." (PMID 33114661, 2020). "Furthermore, we propose that CTGF is a versatile regulator in breast cancer and facilitates SPARC, LOX, ZEB1, VIM and FN1 expression changes." (PMID 33087801, 2020). "Another study indicates that stromal SPARC is pro-metastatic for breast cancer cells." (PMID 28718842, 2017). "SPARC stimulates breast cancer growth and metastasis in in-vivo models." (PMID 28425924, 2017). "Strong expression of SPARC in breast cancer stromal cells is correlated with good prognosis." (PMID 28718842, 2017). "Hypothetically, an accumulation of SPARC in breast cancer cells and stroma could increase its ability to bind albumin, therefore might serve as a predictive marker for nab-paclitaxel." (PMID 28061451, 2017). "In melanoma and breast cancer tissues, tumor cells were the main source of SPARC." (PMID 29156791, 2017). "Forced expression of SPARC in 4T1 breast cancer cell line resulted in reduced tumor growth in vivo." (PMID 27105498, 2016). "However, SPARC clearly enhanced death of TS/A cells supporting its role as a suppressor of breast cancer." (PMID 27105498, 2016). "Thus, up-regulation of THBS1, TNC, FN, SPARC and α-SMA following neoadjuvant chemotherapy was associated with chemotherapy resistance in breast cancer patients." (PMID 27487140, 2016). "SPARC was also found to inhibit proliferation of breast cancer cells in vitro." (PMID 27105498, 2016). "Conversely, hypoxia induces Endothelin 1, which upregulates SPARC, and these biological stimuli may be considered prognostic markers of bone metastasis in breast carcinoma patients." (PMID 27187355, 2016).
breast carcinoma (continued). "Reduced SPARC expression was shown to correlate with poor prognosis in breast cancer patients." (PMID 27105498, 2016). "Therefore, further studies should investigate the potential use of SPARC as a predictive biomarker of responsiveness to nab-paclitaxel therapy in TNBC as well as in other types of breast cancer." (PMID 27421134, 2016). "To clarify whether SPARC had a differential involvement in the various phases of breast carcinoma progression, we evaluated SPARC expression in dysplastic lesions, primary ductal carcinoma and bone metastasis using human specimens pair-matched (n = 5)." (PMID 26703564, 2015). "Our hypothesis was that SPARC might be a key molecular signal released from primary breast carcinoma and/or locally produced in bone metastasis to influence the bone niche formation in the secondary site." (PMID 26703564, 2015). "Based on transgenic models of breast cancer, SPARC expression could be used as a potential prognostic biomarker of tumour severity and/or aggressiveness." (PMID 26703564, 2015). "However, breast cancer associated tumor suppressor genes such as RARRES1, SPARC, SOCS3, and LIF were also up-regulated in T47D cells." (PMID 25776849, 2015). "SMOC1 is SPARC (secreted protein, acidic and rich in cysteine) related modular calcium binding 1 and has been found a correlation with malignant progression, such as brain tumor, colorectal cancer and breast cancer." (PMID 25436889, 2014). "Limited data are available regarding the potential role of SPARC in breast cancer." (PMID 23638089, 2013). "However, on restricting the analysis according to breast cancer subtype, we found that high SPARC expression was associated with a trend of worse RFS in patients with basal and HER2-breast cancer." (PMID 23638089, 2013). "The activity of the human SPARC promoter requires a purine-rich region with GGAGG repeats (within the -120/-70 fragment) in human breast cancer MCF7 cell line, and the transactivation of the SPARC promoter is dependent on the transcription factor Sp1/3 in Drosophila SL2 cells." (PMID 20687958, 2010). "Furthermore, suppression of SPARC expression using antisense RNA inhibited motility and invasion of human breast cancer cells in vitro." (PMID 20525171, 2010). "Our results also suggest that higher expression and secretion of SPARC might be correlated with lower metastatic potential of mammary carcinoma cells." (PMID 20687958, 2010). "In this study, we detected the SPARC expression level and its secretion into milieu using three different mammary carcinoma cell lines with different levels of metastatic potential: highly metastatic 4T1, moderately metastatic 168 FARN and non-metastatic 67NR cell lines." (PMID 20687958, 2010). "Finally, our results demonstrated that fenretinide-induced expression of SPARC contributes significantly to a decreased invasion of mammary carcinoma cells." (PMID 20687958, 2010). "By reanalyzing these scRNA‐seq datasets, we noticed that SPARC mRNA was expressed by different CAF subsets, especially myofibroblast‐like and inflammatory‐like CAFs, as well as POSTN, a gene encoding periostin, a protein that is secreted by CAFs with pro‐tumor activity in breast cancer." (PMID 36346290, 2023). "It has been postulated that SPARC may also play a role in different types of cancer, and in some cases, it has promoted the inhibition of breast cancer; SPARC is expressed in grade 3 tumors, but other studies have shown that higher expression of SPARC correlated with decreased metastasis." (PMID 36430810, 2022). "However, due to the very low amount of M-MDSC in our mammary tumor models we were unable of testing whether SPARC could also influence the activity of the monocytic subset." (PMID 31281314, 2019). "SPARC may play an important role in the progression of breast cancer." (PMID 27421134, 2016). "However, the role of SPARC in breast cancer development and progression is controversial." (PMID 27421134, 2016).
breast carcinoma (continued). "However, an opposite correlation has also been demonstrated, suggesting that SPARC may be able to inhibit tumorigenesis or tumor progression in breast cancer, hepatocellular carcinoma, prostate cancer, colorectal cancer, and ovarian cancer." (PMID 22879971, 2012). "However, there are conflicting reports about the precise role of SPARC in breast cancer." (PMID 18328103, 2008). "Also, SPARC has been reported to play a role in migration of breast cancer cells to bone." (PMID 18328103, 2008). "This study systematically explored the expression pattern and clinical significance of SPOCK1 (SPARC/osteonectin, CWCV and Kazal-like domains proteoglycan 1) across multiple cancer types, with a particular focus on its role in breast cancer." (PMID 40837013, 2025). "Secreted protein acidic and rich in cysteine (SPARC) expression has been proposed as a prognostic and predictive biomarker for some cancer types, but knowledge about the predictive value of SPARC polymorphisms in the context of neoadjuvant therapy for breast cancer (BC) is lacking." (PMID 38137452, 2023). "As these two meta‐analysis indicated that SPARC was expressed in different CAF subtypes, another scRNA‐seq dataset (n = 8 patients with breast cancer) that identified different myCAF and iCAF clusters was analyzed." (PMID 36346290, 2023). "Potential therapeutic inbreast cancer by regulating breast cancer-related genes,including SERPINE1, PGAP3, MAP3K1, MAPK1, GSTO2, VIM, SPARC, and FGF2." (PMID 37191432, 2023). "For instance, Massaque and colleagues identified 18 genes, including IL13Ra2, SPARC, MMP1, and MMP2, which can lead to breast cancer metastasis to the lungs." (PMID 35045088, 2022). "We suggest that stromal SPARC plays a role in regulating ECM production and alignment in breast cancer, and that further work should be done to characterize the role that SPARC plays in the stroma as compared to the tumor." (PMID 33534863, 2021). "Breast cancer cells, once nested to bone, undergo partial osteomimicry by acquisition of typical bone cell markers including ICAM-1, CDH11, OPN, osteonectin (SPARC), osteocalcin (BGLAP) and cellular communication network factor 3 (CCN3)." (PMID 34831167, 2021). "Reduced CTGF expression led to increased CD44, SPARC, and FN1 expression in mesenchymal transformed breast cancer cells." (PMID 33087801, 2020). "In human breast cancers, myeloid-derived suppressor cells (MDSC) of polymorphonuclear (PMN), or monocytic origin express the ECM glycoprotein SPARC." (PMID 33187209, 2020). "For example, breast cancer patients with high tumor SPARC expression were seriously more sensitive to an albumin-bound paclitaxel 22, potentially because of the strong binding capacity of SPARC to albumin, which could lead to the accumulation of paclitaxel in local tumor microenvironment." (PMID 31897236, 2020). "Gene set analysis revealed that in human breast cancer cell lines the expression of these seven genes (MUC1, PLAU, FABP7, SPARC, HAS2, HAS3, SOX4) are higher in basal-B subtype compared to other subtypes." (PMID 29435170, 2018). "Cell growth kinetics was evaluated in control and EPCR and SPARC/osteonectin, Cwcv, and kazal-like domains proteoglycan (SPOCK1/testican 1) silenced breast cancer cells in 2D, 3D, and in co-culture conditions." (PMID 28103946, 2017). "This is in line with a previous study on breast cancer cells showing that C1QTNF6, SPARC, and COL4A2 were targeted by miR-29b." (PMID 29176935, 2017). "Given that MMP2, COL1A1 and SPARC are all pro-metastatic genes, we suggest these genes play crucial roles in LOX+ breast cancer metastasis." (PMID 27147578, 2016). "In mammary carcinoma, Brg-1, a SWI/SNF chromatin remodeling complex ATPase, was shown to interact with Sp1 to activate SPARC transcription." (PMID 25657638, 2014).